CD9 (CD9 molecule)
Diseases named in the same sentence as CD9 in open-access papers (continued):
Sharing a sentence is not in itself a finding about the gene and the disease.
glioma (continued). "To analyze the importance of CD9 and CD81 expression for patients with glioma, we compared gene expression of both tetraspanin genes in glioblastoma (GBM." (PMID 36203458, 2022). "CD9, an early fusion molecule, stabilizes gp130 by preventing its ubiquitin‐dependent lysosomal degradation to promote STAT3 activation in glioma stem cells." (PMID 31837208, 2020). "In contrast, CD9 knockdown enhanced both basal and EGF-induced invasion of glioma cells, consistent with its anti-invasive role as shown in prior studies." (PMID 26377974, 2015). "It has been also noticed a total lack of correlation between tetraspanin CD9 and tumor or glioma stem cell marker on EVs in the subjects from these two clusters." (PMID 40106404, 2025). "This targeting ability is attributed to specific surface moieties retained from the parent cells, including tetraspanins (CD9, CD63, CD81), integrins (e.g., αvβ3, α6β4), and phosphatidylserine, which interact with overexpressed receptors on the glioma endothelium and tumor cells." (PMID 40725021, 2025). "Since we barely detected CD63-positive sEVs in supernatants of our glioblastoma cells in preliminary experiments, we focused our examinations on the expression of CD9 and CD81 in human glioma tissues using accessible online data and in the different glioblastoma cells." (PMID 36203458, 2022). "Interestingly, tetraspanin CD9, normally enriched in exosome membranes, has recently been reported to stabilize gp130, thereby facilitating activation of STAT3 signaling in glioma stem cells." (PMID 29867925, 2018). "Our results indicate that the blood of both glioma patients and non-cancer controls contain a population of CD9+ exosomes." (PMID 29383115, 2017). "The combined detection of CD9, survivin and GFAP markers on the surface of serum-derived exosomes from glioma patients by imaging flow cytometry may provide another useful tool for monitoring tumor status in patients receiving survivin-based immunotherapies." (PMID 29383115, 2017). "In glioma patients, a relatively large fraction of the CD9+ exosomes were also GFAP-positive (mean = 25.1%); whereas, a small but detectable fraction (mean = 2.9%) of CD9+ exosomes from control individuals had GFAP on their surface (an 8.7-fold difference)." (PMID 29383115, 2017). "In glioma patients, baseline CD9+/GFAP+/SVN+ exosome levels had no apparent correlation with percentage of survivin-positive cells detected in tumor tissue by immunohistochemistry." (PMID 29383115, 2017). "In glioma, a study exploring EVs released by proneural, and mesenchymal glioma stem cells (GSCs) identified that proneural GSC-derived EVs lacked canonical EV-based tetraspanin markers such as CD9, CD63, and CD81, while they were abundant in mesenchymal GSC-derived EVs." (PMID 38760427, 2024). "In contrast to glioma stem cells, U87 cells showed no overexpression of stem cell markers, such as SOX2, ZEB1, ATXN1, ALCAM, CD9, ITGA7, CD44 and CHI3L1." (PMID 34680293, 2021).
Obesity (29 papers, 2013 to 2026). Accumulation of substantial excess body fat. "Loss of myeloid CD9 reduces adipose tissue fibrosis, increases visceral adipose tissue accumulation, and improves global metabolic outcomes during diet-induced obesity." (PMID 41665945, 2026). "In obesity, there was a significant increase in lipid-associated CD9+ macrophages, along with reduced miR-690 levels in both ATMs and APCs, resulting in a great reduction in the APC population." (PMID 40912400, 2025). "One important question on the obesity-associated ATM accumulation is the obscure relationship between the newly-identified CD9+ and Trem2+ ATM populations and the originally identified ‘M1-like’ CD11c+ ATMs." (PMID 40244655, 2025). "High-resolution investigations first delineated obesity-associated lipid-laden ATMs with CD9 expression, which were further demarcated by Triggering receptor expressed on myeloid cells 2 (Trem2) expression in both mice and humans." (PMID 36875144, 2023). "The pan-marker CD68, proinflammatory marker iNOS, and novel markers TREM2 and CD9 are widely used markers in macrophages that are strongly associated with obesity and diabetes." (PMID 36814909, 2023). "Consistent with previous reports, obesity enhanced the proportion of Itgax+ (encoding CD11c) and Cd9+ ATMs (cluster 0) and Plac8+ monocytes (cluster 4) and reduced the proportion of Lyve1+ and Cd163+ ATMs (cluster 1) and Lyz1+ monocytes." (PMID 34676827, 2021). "CD9 and Trem2 were the plasma membrane markers of this pro-inflammatory, lipid-associated macrophage, and the lean mice receiving the CD9 + macrophages from obese mice displayed severe metabolic disorders, which indicated the causality between this macrophage subtype and obesity." (PMID 37892414, 2023). "In contrast, miR-690 abundance was greatly repressed in both CD9-and CD9+ ATMs in obesity, concomitant with lowering APC miR-690 abundance and population." (PMID 40912400, 2025). "Our studies also showed that IRE1α inhibition diminishes the obesity-elicited pro-inflammatory ATM subpopulations including the newly identified CD9+ ATMs and adipose inflammation which is known to suppress thermogenesis." (PMID 40244655, 2025). "This switch is characterized by extracellular matrix (ECM) remodeling and upregulation of the fibrosis marker CD9, even before the onset of obesity." (PMID 40836034, 2025). "For instance, PDGFRα‐positive adipocyte progenitor cells become CD9‐high and acquire profibrotic properties during the development of obesity." (PMID 40667744, 2025). "First, we confirmed that the newly identified populations of proinflammatory ATMs (i.e., CD9+ and Trem2+) are induced under high fat diet-mediated obesity and determined their relationships with the originally identified “M1-like” CD11c+ ATMs." (PMID 39071288, 2025). "The number of CD9-positive events was also higher in plasma EV samples from people with obesity, but the percentage of CD9-positive particles of all particles was on the same level in both sample types." (PMID 38965596, 2024). "According to the CD9 expression, we can differentiate CD9+ ATMs, which are increased in obesity and are mostly derived from the bone marrow, and CD9- ATMs, which are responsible for angiogenesis." (PMID 39063610, 2024). "Three samples, two from subjects with obesity and one from a normal-weight subject were incubated with the mixture of CD9 and adiponectin antibodies." (PMID 38965596, 2024). "RNA-sequencing identified CD9-expressing, pro-inflammatory ATMs that surround dead adipocytes are abundant in obesity." (PMID 36875144, 2023). "Altogether, these experiments demonstrate that the CD9+ macrophages that accumulate during obesity are senescent cells that exhibit less phagocytic capacity and have a high level of secretory capacity." (PMID 35181634, 2022).
Obesity (continued). "A more specific study showed that a subset of PDGFRα+ cells with high CD9 expression, induced by obesity, originates pro-fibrotic cells, while those with low CD9 expression are committed to adipogenesis." (PMID 32553115, 2020). "HFD feeding triggers the recruitment of PDGFRα+ cells and obesity induces CD9 expression in PDGFRα+ cells, which become fibrotic cells." (PMID 32553115, 2020). "However, the mRNA levels of individual Tnfα, Il1b, or Mcp-1 are differentially expressed among CD9+CD11c−, CD9−CD11c+, and CD9+CD11c+ ATMs, suggesting functional heterogeneity even among proinflammatory ATMs during obesity." (PMID 39071288, 2025). "Similarly, Trem2+ ATMs (F4/80+CD11b+Trem2+) expand significantly in the eWAT of mice with obesity, most of which also express CD9." (PMID 39071288, 2025). "Transplantation of CD9+CD55low APCs from T2DM patients into mouse adipose tissue induces glucose intolerance and insulin resistance, while genetic knockout or pharmacological depletion of this subpopulation ameliorates obesity-associated metabolic dysfunction." (PMID 41303487, 2025). "STF suppresses the accumulation of metabolically active CD9 or Trem2-expressing ATMs in obesity." (PMID 40244655, 2025). "However, the mRNA levels of individual Tnfa, Il1b, or Ccl2 are differentially expressed among CD9+CD11c-, CD9-CD11c+, and CD9+CD11c+ ATMs, suggesting functional heterogeneity even among proinflammatory ATMs during obesity." (PMID 40244655, 2025). "Interestingly, the number of CD9-positive particles of subjects with obesity positively correlated with BMI, as well as SAT TNF expression levels." (PMID 38965596, 2024). "Adoptive transfer of CD9+ ATM to lean mice leads to the up-regulation of genes related with obesity, suggesting that CD9+ ATM may promote the development obesity and metabolic diseases." (PMID 37153549, 2023). "In addition, lean SAT and VAT vesicles contained fewer CD9 positive vesicles than BAT, and an increment of CD9 positive vesicles was observed with obesity in VAT and BAT." (PMID 36142750, 2022). "Additionally, CD9+ metabolically active macrophages, characterized by high lipid metabolism gene expression, play a beneficial role in clearing dead adipocytes and maintaining tissue homeostasis in obesity." (PMID 41303487, 2025). "However, the contribution of CD9 to the activation and function of LAMs during obesity is unknown." (PMID 41665945, 2026). "These infiltrated cells represent a novel family of cell subtypes, which are CD9+ and DARC+ macrophages, principally localized in crown-like structures within adipose tissue during obesity." (PMID 40284173, 2025). "Serum levels of EV markers CD9/CD63 and sonic hedgehog N-terminal (Shh-N) were significantly higher in adolescents with obesity compared to both healthy controls and those with T2D." (PMID 41150813, 2025). "First, we confirmed that the newly identified populations of proinflammatory ATMs (i.e. CD9+ and Trem2+) are induced under HFD-mediated obesity and determined their relationships with the originally identified ‘M1-like’ CD11c+ ATMs." (PMID 40244655, 2025). "In addition, we found that while only approximately 47% of the CD9+ ATMs (F4/80+CD11b+CD9+) express Trem2, an overwhelming majority (~86.7%) of Trem2+ ATMs (F4/80+CD11b+Trem2+) expresses CD9, corroborating a previous finding that Trem2+ expression emerges after CD9+ ATMs over the course of obesity." (PMID 40244655, 2025). "In white adipose tissue, CD9+TREM2+ macrophages correlated with the severity of inflammation and influenced obesity pathology." (PMID 36814909, 2023). "In summary, the presence of TREM2+CD9+ adipoclasts or adipoclasts precursors seems to correlate with WAT inflammation and the severity of obesity-related pathologies." (PMID 34794433, 2021).
Obesity (continued). "First, functional deficiency of the tetraspanin CD9 might be a common mechanistic component underlying inflammation caused by inactivation of HDAC (e.g., LPS or cigarette smoke exposure) and inflammation induced by abnormal lipid metabolism (e.g., obesity or metabolic syndrome)." (PMID 24040034, 2013). "Notably, TREM2+ and CD9+ LAMs were found to be part of CLS and their frequency increased with obesity in mice and humans with a shift toward a pro-inflammatory polarization characterized by IL-1β and TNF production." (PMID 34794433, 2021). "In obesity, several proinflammatory subpopulations of adipose tissue macrophages (ATMs) identified hitherto include the conventional “M1-like” CD11C-expressing ATM and the newly discovered metabolically activated CD9-expressing ATM; however, the relationship among ATM subpopulations is unclear." (PMID 39071288, 2025). "Thus, we do not recommend Cd9 as a LAM marker, as it is only shown in certain conditions, such as obesity." (PMID 39872854, 2023). "Interestingly, as in obesity, ATMs in CLS were predominantly positive for the commonly used M1 markers CD11c, CD86, and CD9, whereas interstitial ATMs showed almost no expression of these marker proteins." (PMID 34091595, 2021).
ovarian carcinoma (29 papers, 2008 to 2025). A malignant neoplasm originating from the surface ovarian epithelium. "CD9 down regulation on ovarian cancer cells seem to be associated to higher histological grade and metastatic progression." (PMID 19079610, 2008). "The study comprehensively investigates the roles of SPP1, SLPI, and CD9 in ovarian cancer, providing insights into their functions in skeletal development, immune regulation, and tumor progression." (PMID 40196737, 2025). "Western blot analysis confirmed the presence of exosome-specific protein markers, including CD9, CD63, and tumor susceptibility gene 101 (TSG101), in ovarian cancer (OC) ascites." (PMID 41331197, 2025). "On the other hand, other groups reported poor outcomes for breast and ovarian cancer patients with high CD9 expression using Abcam monoclonal antibody EPR2949 or an antibody from Millipore." (PMID 37007105, 2023). "CD9 upregulation was also detected in ovarian carcinomas by expression profiling and immunohistochemistry." (PMID 37007105, 2023). "By using ExoSearch, it was shown that ovarian cancer patients overexpressed the CA-125, EpCAM, CD9, CD81 and CD63 markers." (PMID 37504087, 2023). "In ovarian cancer, the downregulation of CD9 attenuated the expression of several integrins and rearranged junctional and cytoskeletal molecules which was associated with weaker adhesion to the extracellular matrix." (PMID 37007105, 2023). "The results showed significant levels of CD63 and CD9 expression on the surfaces of exosomes in ovarian cancer ascites." (PMID 36741380, 2022). "An antibody functionalized microfluidic platform was reported for the detection of biomarkers that exist in the membranes of cancer exosomes, i.e. EpCAM, CD9, in order to dissociate exosomes from ovarian cancer serum." (PMID 36259505, 2022). "By using a 3D novel engineered ExoProfile chip, diagnostic power of seven markers (EGFR, HER2, CA125, FRα, CD24, EpCAM, and CD9 plus CD63) were evaluated with AUC = 1 in ovarian cancer derived exosomes." (PMID 31718609, 2019). "In particular, CD9 has been shown to promote ovarian cancer cell dissemination by influencing integrin activation." (PMID 25356755, 2014). "Our results differ from previous work indicating that downregulation of CD9 correlates with decreased levels of α5 and β1 integrins, contributing to dissemination of ovarian carcinomas." (PMID 24466195, 2014). "A recent study produced a contradictory result that revealed CD9 to be upregulated in ovarian carcinomas, particularly in serous-type ovarian cancer." (PMID 24520284, 2014). "Additional evidence supporting the suppressive role of CD151-α3β1 integrin complexes in ovarian cancer comes from the loss of tumor-promoting molecules within CD151-deficient TEMM, such as CD9 and claudin-3." (PMID 25356755, 2014). "SPP1, SLPI, and CD9 and their mechanisms of action may be potential targets for the treatment of ovarian cancer with succinic acid." (PMID 40196737, 2025). "In ovarian cancer, NK cells acquire CD9 from ovarian cancer tumor cells, supressing cytotoxicity." (PMID 37205115, 2023). "ExoCounter allowed us to find high expression of CD9+/HER2+ sEVs in sera of breast and ovarian cancer patients compared to healthy donors." (PMID 37504087, 2023). "In this study, we defined the release of exosomes from ovarian cancer cells as the accumulation (in exosome-free incubation medium) of CD63 and CD9 positive, particulate protein with a density of 1.15 to 1.19 g/ml." (PMID 24393345, 2014). "Exosomes in the ascites derived from ovarian cancer carried the marker set EpCAM, CD24 and CD9 that appear to exist on a common exosome type." (PMID 21651777, 2011). "This study investigated three key genes in ovarian cancer (OV), namely, SPP1, SLPI, and CD9." (PMID 40196737, 2025).
ovarian carcinoma (continued). "Detection of a panel of biomarkers (EGFR, CA125, EGFR2, folate receptor α, CD9, CD24, and EpCAM) in circulating exosomes not only identified ovarian cancer patients from control subjects but also distinguished between early- and advanced- stage ovarian cancer." (PMID 38796525, 2024). "The role of CD9 expression on stromal cells in ovarian cancer has not been established." (PMID 19079610, 2008). "While CD81 (as well as CD9 and CD63) is not universally present in all EVs, our previous work has shown that preselecting a subpopulation of plasma EVs using CD81 can reproducibly detect ovarian cancer-associated biomarkers using these nano-engineered microfluidic chips." (PMID 37884576, 2023).